FLT1P1 (FLT1 pseudogene 1)
Synonyms: LOC391533
Gene: Processed pseudogene on chromosome 3 (46,142,358 to 46,143,677, reverse strand). Ensembl gene ENSG00000229515.
Diseases named in the same sentence as FLT1P1 in open-access papers:
FLT1P1 is named in the same sentence as 4 diseases in open-access papers, as found by Europe PMC text mining. Sharing a sentence is not in itself a finding about the gene and the disease. The quoted sentences say what the papers report.
COVID-19 (2 papers, 2023). A disease caused by infection with severe acute respiratory syndrome coronavirus 2. "By conducting SMR and HEIDI methods, several non-MHC region SNPs were identified as common shared genetic loci including rs143334143 (TCF19), rs2277732 (DPP9), rs77534576 (DLX3), and rs13081151 (FLT1P1), among others, which were significantly associated with OA-critical COVID-19 combined trait." (PMID 37398645, 2023). "Rs2277732 (DPP9), rs13081151 (FLT1P1), and rs11085727 (TYK2), among others, were considered significantly associated3with OA-COVID-19 hospitalization combined trait." (PMID 37398645, 2023).
preeclampsia (1 paper, 2023). Preeclampsia is a hypertensive disorder of pregnancy that is characterized by new-onset hypertension with proteinuria presenting after 20 weeks of gestation, and depending on mild or severe forms may initially present with severe headache, visual disturbances, and hyperreflexia. "FMS-associated tyrosine kinase 1 pseudogene 1 (FLT1P1) and FLT1 have been shown to regulate trophoblast proliferation and angiogenesis in preeclampsia." (PMID 37389124, 2023). "Hence, the occurrence and development of preeclampsia may be owing to the abnormal regulation of FLT1P1 and FLT1 expression; this indicates that FLT1P1 and FLT1 are promising biomarkers for the diagnosis of preeclampsia." (PMID 37389124, 2023).
tumor (2 papers, 2018 to 2024). "FLT1P1 inhibits both VEGFR1 and non-cognate VEGF-A expression, suppressing tumor cell proliferation and xenograft tumor growth." (PMID 38808892, 2024).
FLT1P1 also shares sentences with these, for which no sentence is quoted: colorectal cancer (1 paper).